CAV1 (caveolin 1)
Diseases named in the same sentence as CAV1 in open-access papers (continued):
Sharing a sentence is not in itself a finding about the gene and the disease.
cancer (continued). "In this article, we review evidences that CAV1 – a protein known to regulate cholesterol distribution, signal transduction, cell migration, and endocytic vesicular trafficking – represents one such regulator of cell metabolism, especially in cancer cells." (PMID 27852311, 2016). "This CAV1-mediated metformin sensitivity may extend beyond glycolysis since the drug also acts on complex I of the electron transport chain in cancer cells; hence it offers further clue for investigating CAV1 expression and response to anti-metabolic drugs." (PMID 27852311, 2016). "Altogether, these observations strongly link CAV1 expression to mitochondrial function, and could be relevant in understanding how CAV1 affects mitochondrial bioenergetics in cancer." (PMID 27852311, 2016). "Caveolin-1 (CAV1) is a scaffolding protein that plays a dual role in cancer." (PMID 27259249, 2016). "Several studies have reported that CAV1 modulates fatty acid metabolism in normal and cancer cells." (PMID 27852311, 2016). "CAV1 resides at the 7q region and is heterogeneously expressed in cancer." (PMID 28018857, 2016). "Increased CAV1 expression has been correlated with metastasis in a number of human cancers." (PMID 27259249, 2016). "It is therefore conceivable that understanding the expression and function of CAV1 in cancer could serve as a pointer for exposing novel metabolic genes or pathway alterations of clinical importance." (PMID 27852311, 2016). "Regulating cell growth through TNF-alpha and CAV1 is another way that flavonoids might affect cancer." (PMID 27023590, 2016). "Caveolin-1 (Cav-1), a principal structural component of caveolar membrane domains, contributes to cancer development but its mechanobiological roles under low shear stress (LSS) conditions remain largely unknown." (PMID 26919102, 2016). "For instance, while CAV1 overexpression may drive glycolysis and glucose dependency, its knockdown also enhances glycolytic phenotypes in cancer and normal cells." (PMID 27852311, 2016). "There is abundant evidence that CAV1 plays diverse roles in normal and cancer cell metabolism, which appears to be spatiotemporal and dependent on cell types, microenvironmental factors, nutritional availability and probably even additional perturbations, e.g. hypoxia or drug treatment." (PMID 27852311, 2016). "However, the contribution of this modification to the dual role of CAV1 in cancer remained unexplored." (PMID 27259249, 2016). "Understanding the molecular interplay between CAV1 and metabolism could help uncover druggable metabolic targets or pathways of clinical relevance in cancer therapy." (PMID 27852311, 2016). "Moreover, TGF-β triggers in fibroblasts increased oxidative stress, autophagy/mitophagy, aerobic glycolysis, and downregulation of Cav-1: these alterations can extend to surrounding fibroblasts and support cancer cell growth." (PMID 27595103, 2016). "FASN modulates Cav-1-dependent signaling pathways and controls proliferation of cancer cells." (PMID 27980732, 2016). "CAV1 and PTRF are previously reported as cancer-associated caveolae genes." (PMID 28155687, 2016). "Cav-1 expression was significantly upregulated in a series of drug-resistant cancer cells." (PMID 26431273, 2015). "Moreover, Cav-1 was highly expressed on cancer stem cells (CSCs) and affected CSCs’ chemosensitivity." (PMID 26431273, 2015). "Finally Cav-1 enriched cancer cells acquired drug-resistant properties and stem-like characteristics." (PMID 26431273, 2015). "Studies indicate an elevation of Cav-1 in cancer cells after chemotherapeutic exposure." (PMID 26431273, 2015). "Finally, a Cav-1 fluctuation model during cancer development is provided and Cav-1 is suggested to be a stress signal and cytoprotective." (PMID 26431273, 2015). "CAV1 delivery to the TME involved cancer cell-derived exosomes." (PMID 25633184, 2015).
cancer (continued). "However, loss of CAV1 expression was observed in androgen dependent LNCaP cells while increased expression occurred in PC3 cells and tissues from advanced cancer." (PMID 26112043, 2015). "Recent work also indicates that Cav-1 may be a stress-related molecule mediating cancer drug resistance and metastasis." (PMID 26431273, 2015). "Also, Cav-1 was found to be a critical regulator of aerobic glycolysis, a key metabolic switch influencing cancer chemosensitivity." (PMID 26431273, 2015). "Accordingly, the involvement of parkin in many physiological and pathological conditions such as metabolism and cancer may be mediated by cav-1 expression." (PMID 26627850, 2015). "Furthermore, larger clinical studies are needed to confirm the pathological significance of Cav-1 in cancer onset and response to conventional therapy." (PMID 26431273, 2015). "Meanwhile, autophagic activation by Cav-1 silencing may be a novel strategy for overcoming cancer drug resistance." (PMID 26431273, 2015). "A biphasic role of Cav1 in signal transduction and cancer has been thoroughly documented." (PMID 26315660, 2015). "Previous studies of the role of Cav1 in EMT were mostly conducted in experimental models of cancer." (PMID 25550395, 2015). "Recent studies have begun to reveal the complexity of caveolin-1 function in cancer." (PMID 25924234, 2015). "Our study suggests the novel hypothesis that the Cav-1 protein has a positive regulatory function in the process of cancer cell metastasis." (PMID 24955034, 2014). "Likewise, caveolin-1 (Cav-1), a major protein component of caveolae, was reported to regulate cancer cell activities." (PMID 24967418, 2014). "Our results reveal the positive role of Cav-1 on lamellipodia formation and cancer cell migration." (PMID 24955034, 2014). "Several reports indicate that caveolin-1 has a role in cancer development and progression." (PMID 25243186, 2014). "However, details of the molecular mechanisms by which CAV1 regulates autophagy in cancer cells remain to be determined." (PMID 25328887, 2014). "Thus, hypermethylation of CAV1 promoter has been shown to maintain it at low expression levels in some types of cancer such as breast and colon." (PMID 25313138, 2014). "In addition to staining neoplastic epithelial cells, Cav-1 was also present in fibroblasts of the desmoplastic cancer stroma." (PMID 24949874, 2014). "Moreover the affinity of albumin for caveolin-1 is believed to target the drug specifically to cancer cell populations expressing high levels of this surface protein." (PMID 25015569, 2014). "Given the parallels between the roles of CAV1 and autophagy in cancer, it is intriguing to speculate that there might be a connection between the two." (PMID 25328887, 2014). "More recently, studies have concentrated on the gene expression of Cav-1 in cancer cells." (PMID 25202343, 2014). "The function of CAV1 in cancer is reported to be cancer type- and stage-dependent." (PMID 25180681, 2014). "Cellular levels of Cav1 have been shown to be increased in multidrug resistant cancer cells." (PMID 23521716, 2013). "In the present study, the role of exogenous natural plasmalogen in cancer cell proliferation and whether there is a direct or indirect interaction between exogenous natural plasmalogen and caveolin-1 were investigated." (PMID 24143228, 2013). "Also, Cav-1 was shown to reduce anoikis response that allows cancer cells expressing high Cav-1 to survive for long time and adhered to the distant sites." (PMID 23460862, 2013). "The contribution of Cav1 to cancer progression appears to be complex and remains controversial." (PMID 23521716, 2013).
cancer (continued). "Having shown that Cav-1 attenuated cancer ability to adhere to an endothelium by decreasing cellular hydrogen peroxide and hydroxyl radical up-regulations, and evidence indicated that Cav-1 regulates several cell behaviors during cell detachment through PI3K/Akt pathway." (PMID 23460862, 2013). "This indicates that Cav-1 negatively regulates cancer cell adhesion to vascular endothelium." (PMID 23460862, 2013). "Caveolin-1, a principal structural component of caveolar membrane domains, contributes to cancer development, but its precise role in cancer regulation remains unclear." (PMID 23521716, 2013). "As the low expressing cell lines show a more differentiated phenotype, as compared to the high expressing ones, it can be hypothesized that TGF-β mediated cancer EMT is accompanied with an increase of caveolin-1 expression." (PMID 23339737, 2013). "Although lacking a fundamental mechanistic understanding to explain a fully Cav1-induced malignant phenotype, it is well documented that Cav1 cooperates with other proteins to promote cancer dissemination by affecting critical functions of cellular maintenance and homeostasis." (PMID 23521716, 2013). "Furthermore, the ectopic overexpression of Cav-1 attenuated the ability of the cancer cells to adhere to endothelium while shRNA-mediated Cav-1 knock-down exhibited the opposite effect." (PMID 23460862, 2013). "Cav-1 expression has been shown to be elevated in various malignancies such as colon, thyroid, lung and bladder cancers." (PMID 22353809, 2012). "Taking into consideration these conflicting in vitro and clinical results, we postulate that the functions of cav-1 may have different roles in various cancer cell types." (PMID 22200856, 2012). "This apparent contradiction may be explained by different interacting partners during cancer progression, and it is proposed that in vivo, CAV1 plays a tissue and stage specific modulatory role in cancer." (PMID 21471610, 2011). "Caveolin-1 (Cav-1), a major structural protein of caveolae, is involved in many physiologic and patho-physiologic processes such as cardiovascular diseases, neurological disorders, and cancers." (PMID 20700465, 2010). "In accordance with this, Cav1 has been shown to have a role in carcinogenesis, though its mechanism may vary with cancer type." (PMID 19317917, 2009). "Despite the plethora of pathways that have been identified since then linking caveolin-1 function to cancer, the precise role of this protein remains unclear." (PMID 18400052, 2008). "Therefore, it is tempting to propose as a working model that caveolin-1 effects in a given cancer cell depends on the ‘transformation status’." (PMID 18400052, 2008). "Our results provide the first clinical evidence that caveolin-1 cooperates with an activated AKT/mTOR pathway in cancer and may play an important role in disease progression." (PMID 18283322, 2008). "Hypermethylation of the caveolin-1 promoter may also be a mechanism by which its expression is altered in cancer." (PMID 18949068, 2007). "The expression of caveolin-1 protein in carcinomas has also been studied." (PMID 11953823, 2002). "However, the detailed mechanisms of how CAV1 regulates cancer cells remain to be investigated." (PMID 39780187, 2025). "Overall, our work highlights new insight into the morphological diversity and the correlation between cellular shape and phenotype of cancer cells, and provides evidence that Cav-1 could affect cancer cell properties such as self-renewal capacity through maintaining the morphological stability." (PMID 41164943, 2025). "Notably, Cav-1, which was increased in our NCH644 BRAT1 KD proteomic dataset, has been implicated in modulating migration in a context-dependent manner in different cancer types." (PMID 39833546, 2025). "Notably, Cav1 is abundant in TEVs and has been proposed as a biomarker for cancer progression." (PMID 40963741, 2025).
cancer (continued). "Our study adds to this body of work by showing that CAV1 expression is negatively correlated with TKI sensitivity across 785 human cancer cell lines, regardless of origin or mutation burden, suggesting a broader oncogenic role of CAV1 in promoting TKI resistance." (PMID 40715090, 2025). "However, whether Cav-1 is involved in the response of cancer cell to topological structural changes of ECM, and by what mechanisms, remain unknown." (PMID 39318372, 2024). "Cancer cells could regulate the level of Cav-1 to respond to biochemical or biomechanical stimuli." (PMID 39318372, 2024). "Because deacetylated Ago2 K212 is responsible for Ago2/CAV1 interaction and the interaction-mediated miRNA function in cancer cells, we evaluated the effects of Ago2 K212 acetylation on the Ago2/CAV1 interaction-dependent behaviors of cancer cells (i.e., invasion and tumorsphere formation)." (PMID 38649663, 2024). "Since the positive charge of Ago2 K212 is essential for Ago2/CAV1 interaction and acetylation of Ago2 K212 neutralizes the positive charge, we further explored the deacetylases that may attenuate Ago2 K212 acetylation in cancer cells for Ago2/CAV1 interaction." (PMID 38649663, 2024). "Therefore, targeting CAV1 could potentially enhance the effect of ferroptosis and inhibit cancer progression." (PMID 37711170, 2023). "Therefore, CAV1 is an important pathophysiological factor in various types of cancer." (PMID 37642765, 2023). "However, the role of Cav-1 in cancer metastasis is complex and controversial." (PMID 37056561, 2023). "Moreover, the concentration of CAV1 progressing with cancer grade may be related to the decreasing activity of miR-1207-5p, miR-1910-3p, and miR-940." (PMID 37233761, 2023). "In this regard, studying the modulatory effects of miRNAs and lncRNAs on those glycolytic proteins linked with cancer progression, e.g., HK1, GAPDH, PKM2, GLUT1, GLUT3, HIF-1α, CAV1, Ras, HK2, LDHA, PGI/AMF, and PFKFB3, might be very favorable for the design of novel treatments for PC." (PMID 36332600, 2023). "It was speculated that CAV-1 has a dual role in cancer progression and metastasis." (PMID 37516753, 2023). "The role of Cav-1 in cancer progression may vary depending on the type of cancer." (PMID 37056561, 2023). "Finally, it has been found that fibroblasts knocking down Cav-1 may exert an influence on cancer cell metabolism by promoting the production of lactate, a mitochondrial respiration product of synthetic cancer cells." (PMID 36046791, 2022). "Furthermore, a recent study by our group showed that the dephosphorylation of Cav-1 promotes mitophagy and therefore may increase cancer cell survival by eliminating damaged mitochondria." (PMID 35954304, 2022). "This indicated that Cav1 might function as a cancer suppressor in cervical carcinoma cells." (PMID 35897965, 2022). "Here, we address mechanisms associated with CAV1 in cancer drug resistance independent of P-gp." (PMID 35158857, 2022). "Additionally, Cav-1 could significantly inhibit the glycolytic metabolism of cancer cells by inducing the degradation of c-Myc." (PMID 34568078, 2021). "Based on experimental evidence presented in immunoblot analysis and clonogenic assay indicates that the upregulation of caveolin-1 in radiation resistant cells could be one of the radiation induced pathways activated in cancer cells exhibiting radio-resistance phenotype." (PMID 34762666, 2021). "Interestingly—with respect to MPM—it has been reported that Caveolin 1 (CAV1) acts as a multifunctional scaffolding protein which is involved in cancer growth and progression, modulating tissue responses through architectural regulation of the micro-environment." (PMID 34445720, 2021). "In addition, 5 cancer patients genome exhibited deep deletion in CAV-1 gene with only 49% mRNA expression, and one patient had missense mutation with unknown significance." (PMID 34762666, 2021).
cancer (continued). "Therefore, the role of Cav-1 in tumorigenesis remains unclear so far and Cav-1 appears to play a complex role in cancer development." (PMID 33774714, 2021). "Thus, CAV1 expression levels could be used as a biomarker for autophagy inhibitory strategy in cancer treatment." (PMID 34786475, 2021). "Thus, CAV1 appears to be necessary for mitochondrial functionality in normal cells, but the overexpression of CAV1 in cancer cells may promote malignancy in these cells." (PMID 32458269, 2020). "Therefore, the connections and interactions between caveolin-1 expression, cancer progression, and angiogenesis in HCC remain unknown." (PMID 32676485, 2020). "Because Cav-1 may be critical for albumin uptake in tumors and perhaps determine how the patients respond to albumin bound drug, such as cisplatin; it is also verified that over-expressed Cav-1 enhanced the sensitivity to nab-paclitaxel in cancer cell lines and mouse xenograft models." (PMID 31901898, 2020). "Together our results indicate a possible implication of STAT5a in estrogen-stimulated DCIS progression, a phenomenon that could be initiated by a decrease in stromal Cav-1 in vivo, and this possibility will also be tested in future studies with co-cultures with cancer fibroblasts." (PMID 32633727, 2020). "More importantly, multiple antioxidants have been shown to exert antitumor activities in cancer cells and protective activities in normal cells by modulating the Cav-1 pathway, indicating that Cav-1 may be an oxidative stress suppression target for cancer antioxidant prevention." (PMID 31919341, 2020). "Additionally, Cav-1 also acts as a stress signal in multiple cancer cells, and various microenvironmental factors could also be efficient in modulating Cav-1 expression levels." (PMID 32528105, 2020). "However, a considerable amount of evidence now points towards the possibility that “extracellular” CAV1 may be particularly relevant in cancer cell metastasis." (PMID 31362353, 2019). "Caveolin-1 is a scaffolding protein highly expressed in stromal cells involved in a plethora of cellular processes, such as cell proliferation, survival, motility and migration, via the modulation of a variety of signaling pathways aberrantly activated in cancer cells." (PMID 31591367, 2019). "The results provide insights into mechanisms underlying some events mediated by downstream caveolin-1 pathways, including FAK/Src and ROCK/p-myosin light chain (MLC), which are involved in the reorganization of the cytoskeleton, focal adhesion dynamics, cancer cell motility, and adhesion." (PMID 31212828, 2019). "Furthermore, CAV1 is capable of triggering autophagy in normal and cancer cells." (PMID 32082178, 2019). "Caveolin-1- and cavin-1-containing structures appeared close to the plasma membrane around the rear of cells moving in 3D and on 2D rigidity gradients and in cancer cells escaping spheroids in 3D matrix (which share the elongated morphology of cells moving in 3D CDM)." (PMID 31607653, 2019). "Furthermore, CAV1 was recently pinpointed as a target in cancer-related oxidative stress." (PMID 30246033, 2018). "Therefore targeting CAV1 is a promising strategy for overcoming cancer drug resistance." (PMID 30333750, 2018). "Thus, when miR-199a is shown to have decreased expression in SMZL cases, an increased expression of CAV1 could be expected, which has shown to be detrimental in other cancers." (PMID 30042829, 2018). "Most studies suggest that CAV1 may play a positive role in the early stages of cancer onset." (PMID 29190968, 2017). "The relationship between SNPs in CAV1 and cancer risk has not been extensively studied." (PMID 29190968, 2017). "However, there is a disagreement in the data concerning whether Cav-1 plays an inhibitory or stimulatory role in Ras-ERK signaling in cancer cells." (PMID 29141593, 2017).